C6orf163 (chromosome 6 open reading frame 163)
Tractability: PROTAC: ubiquitination databases record sites on it.
Gene: Protein-coding gene on chromosome 6 (87,344,813 to 87,365,463, forward strand). Ensembl gene ENSG00000203872.
Subcellular location (Human Protein Atlas): Nucleoplasm
Genetic constraint (gnomAD): Loss-of-function variants: 19 observed, 25.71 expected, observed/expected ratio (o/e) 0.74, 90% interval 0.51 to 1.08. The upper end of that interval is the gene's LOEUF score, 1.08, which puts it in group 4 of 6, group 1 being the genes least tolerant of losing a copy. Missense variants: 292 observed, 350.14 expected, observed/expected ratio (o/e) 0.83, 90% interval 0.76 to 0.92. Synonymous variants: 96 observed, 112.99 expected, observed/expected ratio (o/e) 0.85, 90% interval 0.72 to 1.01.
Homologues: Orthologues: chimpanzee C6H6orf163 (99% identical), macaque C4H6orf163 (95% identical), dog C6orf163 (82% identical), pig C6orf163 (78% identical), rabbit C6orf163 (78% identical), mouse Gm136 (73% identical), rat C5h6orf163 (70% identical).
Diseases named in the same sentence as C6orf163 in open-access papers:
C6orf163 is named in the same sentence as 1 disease in open-access papers, as found by Europe PMC text mining. Sharing a sentence is not in itself a finding about the gene and the disease.
C6orf163 shares sentences with these, for which no sentence is quoted: parkinsonian disorder (1 paper).